MIR342 (microRNA 342)
Synonyms: hsa-mir-342; MIRN342
Gene: MicroRNA gene on chromosome 14 (100,109,655 to 100,109,753, forward strand). Ensembl gene ENSG00000199082.
Gene Ontology:
Biological process: cellular response to amino acid stimulus; cellular response to forskolin; cellular response to leukemia inhibitory factor; cellular response to lipopolysaccharide; long-term synaptic potentiation; miRNA-mediated post-transcriptional gene silencing; sensory perception of sound
Cellular component: RISC complex
Homologues: Orthologues: macaque mml-mir-342 (100% identical), chimpanzee ptr-mir-342 (99% identical), mouse Mir342 (96% identical), rat Mir342 (96% identical), guinea pig MIR342 (87% identical), pig ssc-mir-342 (75% identical), dog MIR342 (61% identical), rabbit MIR342 (60% identical).
Diseases named in the same sentence as MIR342 in open-access papers:
MIR342 is named in the same sentence as 9 diseases in open-access papers, as found by Europe PMC text mining. Sharing a sentence is not in itself a finding about the gene and the disease. The quoted sentences say what the papers report.
B cell lymphoma (2 papers, 2020 to 2021). "EVL/MIR342 was found to be methylated in 68 (68.7%) B cell lymphoma and eight (24.2%) T cell lymphoma, hence preferentially methylated in B cell lymphoma (P < 0.0001)." (PMID 33076962, 2020). "Epigenetic silencing of MIR342 and its host gene EVL by DNA methylation was reported in colorectal cancer, multiple myeloma, and B cell lymphoma from the patients." (PMID 34526970, 2021).
diabetes (1 paper, 2021). "Since the changes in V̇O2 and RQ were rather mild, the data suggested that the reduction of food intake mainly contributed to the resistance to diet-induced obesity and diabetes in Mir342 (-/-) mice." (PMID 34526970, 2021). "The results suggested that deficiency of Mir342 links to the reduced population and blunted activation of NPY orexigenic neurons, which result in reduced food intake and amelioration of obesity and diabetes under HFHS chow." (PMID 34526970, 2021). "To further give a new insight and investigate the role of Mir342 in obesity and diabetes, we obtained Sanger MirKO ES cell line Mir342 (Mir342tm1Wtsi) from MMRRC (Mutant Mouse Resource & Research Centers) and generated Mir342 knockout mice [Mir342 (-/-)]." (PMID 34526970, 2021). "Mir342 (-/-) mice fed with HFHS chow were protected from obesity and diabetes." (PMID 34526970, 2021).
lipodystrophy (1 paper, 2021). A congenital or acquired disorder characterized by abnormal loss or redistribution of the adipose tissue in the body. "The upregulated expression of Mir342 in white adipose tissue was reported in diet-induced obese mice and ob/ob mice and also in the patients with HIV-induced lipodystrophy." (PMID 34526970, 2021).
metabolic syndrome (1 paper, 2021). A cluster of metabolic risk factors for CARDIOVASCULAR DISEASES and TYPE 2 DIABETES MELLITUS. "Taken together, upregulation of Mir342 and its host gene Evl in brain and adipose tissues tightly links to the metabolic syndrome phenotype of HFHS chow induced obesity mice." (PMID 34526970, 2021).
Obesity (1 paper, 2021). Accumulation of substantial excess body fat. "The functional roles of Mir342 in obesity were demonstrated in the study by investigating Mir342 (-/-) mice, however, the expression of Evl was maintained in Mir342 (-/-) mice and role of Evl in obesity and T2D remains elusive." (PMID 34526970, 2021). "Here, we report the benefits of the deletion of Mir342 gene in C57BL/6JJcl mice fed with HFHS chow, i.e., amelioration of obesity and T2D." (PMID 34526970, 2021). "However, in current investigation, the Evl expression was maintained in brain and adipose tissues from Mir342 (-/-) mice fed with HFHS chow, the roles of Evl in obesity and T2D remains unexplored." (PMID 34526970, 2021). "Mir342 was highly upregulated by HFHS chow in brain in mice, and the striking feature of Mir342 (-/-) mice fed with HFHS is that they were resistant to development of obesity and T2D." (PMID 34526970, 2021).
tumor (1 paper, 2020). "Firstly, EVL/MIR342 methylation was detected in NHL cell lines and primary NHL samples, but not in normal peripheral blood and normal tonsil tissues, and hence tumor-specific." (PMID 33076962, 2020).
MIR342 also shares sentences with these, for which no sentence is quoted: colorectal cancer (1 paper); multiple myeloma (1); T cell lymphoma (1).